RAN (RAN, member RAS oncogene family)
Diseases named in the same sentence as RAN in open-access papers (continued):
Sharing a sentence is not in itself a finding about the gene and the disease.
tumor (51 papers, 2013 to 2025). "The mutations in RAN gene are very likely to play a critical role in pathology-related changes to miRNA transport and expression and thus participate in tumor genesis and development." (PMID 32015773, 2020). "Silencing RAN causes abnormal nucleocytoplasmic transportation of transcription factors in tumor cells." (PMID 29706609, 2018). "Here, we report that TPX2 expression, like RAN, correlates positively with tumor grade, and was associated with poor patient survival and with a short recurrence time in HG serous EOC." (PMID 24625450, 2014). "In a previous study, we reported the observation that RAN staining was positively associated with increased tumor grade in serous EOC." (PMID 24625450, 2014). "Therefore, the mutations in RAN gene are very likely to play a critical role in pathology-related changes to miRNA transport and expression and thus participate in tumor genesis and development." (PMID 32015773, 2020). "Similarly, we observed that DROSHA rs10719 and RAN rs14035 CC genotypes were associated with CRC with respect to the subjects’ tumor sizes." (PMID 26147304, 2015). "In addition, the rs3742330 of DICER1, rs784567 of TARBP2, rs417309 of DGCR8, and rs14035 of RAN as well as rs11077 of XPO5 are associated with the LC progression depending on the tumor size." (PMID 26688807, 2015). "In addition, we found the RAN rs14035 CC genotype was related to a decreased risk of CRC with respect to tumor size and metabolism of homocysteine and folate." (PMID 26147304, 2015). "The subcutaneous xenograft model indicated that RAN overexpression significantly enhanced tumor growth following CRSP8 knockdown." (PMID 40069732, 2025). "The expression of HNRNPU and RAN was also enhanced in tumor tissues, with the lowest expression observed in normal tissues (p < 0.001)." (PMID 39453509, 2024). "Among the T-cell regulatory factors, normal and tumor genes showed prominently distinct Inter-cell Interference Coordination (ICIC), with tumor gene expression higher than normal in RAN, CHK1, and CDK2 cells." (PMID 38714987, 2024). "The functions of RAN are further investigated in vivo by establishing a xenograft tumor model and an inguinal lymph node metastasis model." (PMID 39510185, 2024). "RAN promotes tumor progression through a variety of mechanisms, and the classical one is regulating the nuclear import of critical tumor-promoting transcription factors and the cytoplasmic retention of tumor-suppressing transcription factors." (PMID 39510185, 2024). "The inference is obtained by finding that the high expression of RAN, and associated proteins XPO7 and TPX2, correlates with an increased tumor grading and is strongly related to the poor survival of patients." (PMID 36672435, 2023). "RAN has been identified in various tumors, with high levels related to tumor aggressiveness and metastasis." (PMID 35151325, 2022). "Previous studies have demonstrated that TPI1 and RAN exerted crucial effects on tumor initiation and progression." (PMID 35836227, 2022). "XPOT, a member of RAN-GTPase exportin family, which mediates export of tRNA from the nucleus to the cytoplasm, promotes tumor proliferation and invasion in liver cancer." (PMID 34285249, 2021). "In CRC, miR‐802 reduces the activation of the PI3K/AKT/mTOR pathway by down‐regulating RAN, thereby inhibiting tumor cell proliferation, metastasis, and invasion." (PMID 34558723, 2021). "To examined the effect of RAN/HSBP1 on the tumor formation of OC cells, we transplanted A2780 Lin28A shNC, shRAN (#1 and #2) and shHSBP1 (#1 and #2) cells into the Balb/c nude mice to form tumor, separately." (PMID 32398961, 2020).
tumor (continued). "Silencing of the RAN has been shown by our group to have significant potential in reducing both invasion and proliferation in an aggressive tumour cell line." (PMID 30560466, 2018). "Moreover, CRC tissues exhibit significantly higher levels of RAN expression than normal colorectal epithelial cells, which have been positively associated with depth of invasion, lymph node metastases, distant metastases, tumor differentiation, and tumor–node–metastasis stage." (PMID 26147304, 2015). "In previous studies, we have demonstrated that RAN (RAs-related Nuclear protein), in EOC, is over expressed as tumor grade increases and is strongly associated with poor patient survival." (PMID 24625450, 2014). "Having established the staining pattern for each of the RAN network proteins, we then assessed the staining intensity according to tumor grade." (PMID 24625450, 2014). "Importantly, the translocation of signal transducer and activator of transcription 3 (STAT3) requires RAN to subsequently stimulate cellular differentiation, proliferation, and tumor cell invasion." (PMID 39041645, 2024). "H&E staining of footpad tumor sections showed that the tumor is well demarcated from the muscle tissue and lymphatic vessels maintained simple epithelium after RAN silencing, suggesting that knockdown of RAN inhibited tumor invasion from footpad into muscle tissues and lymphatic vessels." (PMID 39510185, 2024). "Although RCC1 is also expressed in normal cells and can prevent the aging and death of normal cells due to DNA damage, the use of RAN-IP may have an impact on normal cells, but tumor cells are more affected after reducing Ran levels." (PMID 37284316, 2023). "Studies have hypothesized that the RAN rs3803012 G allele might affect the targeting of hsa-miR-199a-3p and result in decreased expression of RAN mRNA in tumor cells, which may affect various miRNA biosynthesis." (PMID 32127945, 2020). "Concerning tumor cell survival, the loss of miR-483-3p leads to overexpression of various anti-apoptotic genes, such as API5, BIRC5 (also termed Survivin) and RAS-related nuclear protein (RAN)." (PMID 32674318, 2020). "Tumor-specific vulnerability to RAN suppression has been demonstrated in a few cell lines." (PMID 32600395, 2020). "Furthermore, the DGCR8 rs1640299, DICER1 rs3742330 and rs13078, RAN rs14035, and XPO5 rs11077 as well as rs784567 of TARBP2 genes single nucleotide polymorphisms have demonstrated an association with tumor progression depending on the lymph node metastases." (PMID 26688807, 2015). "Furthermore, decreasing RAN expression in in vivo mouse xenograft experiments resulted in the arrest of EOC tumor growth." (PMID 24625450, 2014). "An evaluation of molecular signatures based on tumor expression of 20 metastasis-associated microRNAs, a comparison of microRNA expression between tumor and adjacent benign tissue, or the tumor expression of five genes (HN1, RAN, RAMP3, KRT19 and TAF9) can also predict prognosis." (PMID 28943622, 2015). "In this study, RAN was upregulated in HCC and regulated tumor development and progression by influencing T lymphocyte responses in the tumor microenvironment." (PMID 39445019, 2024). "Taken together, our study uncovered the key role of the RSL1D1/RAN/STAT3 regulatory axis in autophagy and tumor progression in CRC, providing a new candidate target for CRC treatment." (PMID 35013134, 2022). "In summary, our study uncovered the key role of the RSL1D1/RAN/STAT3 regulatory axis in autophagy and tumor progression in CRC, highlighting a new target for preventing and treating CRC." (PMID 35013134, 2022). "And after knocking down of RAN or HSBP1 in Lin28A highly expressed OC cells, the survival and invasion of OC cells and tumor size of OC xenograft in nude mice were markedly inhibited and apoptosis was increased." (PMID 32398961, 2020).
tumor (continued). "Molecular studies have shown that down-regulation of RAN results in mitotic defects, the improper localization of TPX2, apoptosis and tumor growth inhibition." (PMID 24625450, 2014). "It expands the mechanism of RAN regulating tumor progression and emphasizes the importance of noncanonical RBPs in tumor regulation." (PMID 39510185, 2024). "We also analyzed the differences in the expression of nomogram model genes (HMGCS2, HNRNPU, RAN) across clinical pathological factors (T, N, M staging, normal vs. tumor)." (PMID 39453509, 2024). "We analyzed the differences in the expression of nomogram model genes (HMGCS2, HNRNPU, RAN) with regard to clinical pathological factors (T, N, M, normal vs. tumor)." (PMID 39453509, 2024). "Functional studies have reported that miR-483-3p may act as an oncogene by targeting BBC3/PUMA directly or tumor suppressor via repression of multiple targets including CDC25A, BIRC5, and RAN." (PMID 29717264, 2018). "Likewise, in vivo, the decrease in RAN in a rat model, led to regression of the EOC tumor." (PMID 36672435, 2023).
infection (8 papers, 2010 to 2023). The state of being infected such as from the introduction of a foreign agent such as serum, vaccine, antigenic substance or organism. "Also in INT-407 cells, Ras related nuclear protein (RAN) signaling, caveolar-mediated endocytosis, tRNA charging and granzyme B signaling were induced only at earlier stages of infection, while remodeling of epithelial adherens junction and phagosome maturation were induced only at later times." (PMID 28491823, 2017). "Apart from proteins discussed in more detail below, other accumulated proteins upon infection included galectin 1 and macrophage-capping protein, and less abundant endoplasmin, GTP-binding nuclear protein RAN, peptidyl-prolyl cis-trans isomerase FKBP4, and adenine phosphoribosyltransferase." (PMID 31708904, 2019).
infectious disease (1 paper, 2011). A disorder directly resulting from the presence and activity of a microbial, viral, or parasitic agent in humans. "Changes in the disease associated cellular functions 'respiratory disease' and 'infectious disease' and the cellular pathway 'RAN signalling' were observed according to our results." (PMID 21933386, 2011).
RAN also shares sentences with these, for which no sentence is quoted: liver cancer (3 papers); cardiovascular disease (2); cyst (2); frontotemporal dementia (2); hepatoblastoma (2); myotonic dystrophy type 1 (2); nasopharyngeal carcinoma (2); neurodegenerative disease (2); abortion (1); acute myeloid leukemia (1); autism spectrum disorder (1); bipolar disorder (1); depression (1); diffuse large B-cell lymphoma (1); end-stage renal disease (1); Epstein-Barr virus infection (1); esophageal squamous cell carcinoma (1); familial melanoma (1); fibrosarcoma (1); gastric ulcer (1); H1N1 virus infection (1); heart failure (1); hydatidiform mole (1); Hypoinsulinemia (1); kidney cancer (1); liposarcoma (1); lymph node metastasis (1); metabolic disorders (1); metastatic melanoma (1); motor neuron degeneration (1).
A further 16 diseases each share a sentence with RAN in 1 paper.